INS (insulin)
Diseases named in the same sentence as INS in open-access papers (continued):
Sharing a sentence is not in itself a finding about the gene and the disease.
liver disease (continued). "If confirmed in future clinical studies, this novel drug could act locally on the liver without modulating glucose and insulin levels and may be an excellent therapy option for other liver disorders." (PMID 38004149, 2023). "However, it should be noted that a recent study showed that as the liver disease worsens to NASH and cirrhosis, there could be a change in the insulin signaling in the liver from resistance to sensitivity." (PMID 36148775, 2022). "Increased sensitivity of the GFC technique also enhances the negative predictive value of the test, as in the second patient we describe, in whom advanced liver disease offered an alternative explanation for fasting hypoglycaemia, rather than insulin sequestration by an insulin autoantibody." (PMID 27588366, 2017). "Insulin mean was high in obese individuals with steatohepatitis (especially in fibrosis patients), and IR was higher (although not significant) in the most advanced stage of liver disease." (PMID 26120587, 2015). "Previous clinical trials where hepatic effects of insulin therapy in diabetic patients were explored, focused on hepatic fat content and non-specific circulating markers of the disease (e.g., aminotransferases) with no evaluation of liver histology and hence on progressive liver disease." (PMID 33596938, 2021). "As a new marker of severity of liver disease independent of body mass index, glutamate–serine–glycine (GSG) index [glutamate/(serine1glycine)] is reported to correlate with hepatic insulin resistance." (PMID 35495903, 2022). "We investigated incretin and insulin secretion after a meal with and without ursodeoxycholic acid (UDCA), a widely used therapeutic agent in liver diseases, in 7 non-diabetic Japanese subjects." (PMID 23450079, 2013). "Notably, the magnitude of benefit varied by comparator drug and baseline liver disease status, with the largest protective effects observed when GLP‐1RAs replaced insulin therapy in patients without established cirrhosis." (PMID 41388641, 2025).
colorectal cancer (205 papers, 1990 to 2026). A primary or metastatic malignant neoplasm that affects the colon or rectum. "This study utilized Mendelian randomization (MR) to assess the causal effects of glycemic traits and fasting insulin levels in patients with type 2 diabetes and colorectal cancer." (PMID 40457130, 2025). "The use of exenatide, liraglutide, or semaglutide was recently shown to associate with an 18% lower risk for colorectal cancer compared with TZDs and 43% lower risk compared with insulin." (PMID 41178720, 2025). "Over a 15-year period, in a study of 1,221,218 drug-naive patients with T2D, it was found that GLP1As reduced the risk of colorectal cancer compared to insulin, metformin, SGLT2 inhibitors, sulfonylureas, and thiazolidinediones." (PMID 40142784, 2025). "While long-acting insulins, such as insulin glargine, have been associated with an increased risk of pancreatic and colorectal cancers, the evidence regarding the impact of insulin treatment on cancer outcomes remains mixed, particularly in patients with BC." (PMID 41303679, 2025). "GLP1As were linked to a reduced chance of colorectal cancer in obese/overweight patients versus insulin, metformin, and/or other diabetes medications." (PMID 40142784, 2025). "Insulin and its analogs, both of which elevate circulating insulin levels, have been documented to heighten the risk of pancreatic and colorectal cancers." (PMID 38254789, 2024). "For example, network pharmacology prediction and molecular docking of active ingredients in Salvia miltiorrhiza have been performed, and SRC, IL6, and INS were found to be associated with colorectal cancer." (PMID 39689118, 2024). "Adipokines, proinflammatory cytokines, insulin, and insulin-like growth factor secreted by adipose tissues have been implicated in the development of colorectal cancer." (PMID 39470380, 2024). "The use of insulin secretagogues was significantly associated with higher colorectal cancer risk in cohort studies (n = 4; RR = 1.21; 95% CI = 1.04–1.40) but not in case–control studies." (PMID 37481610, 2023). "In the current study, an integrated analysis of the association between inflammatory and insulinemic dietary patterns, plasma inflammation, and insulin biomarkers, plasma metabolomics, and colorectal cancer risk, was conducted." (PMID 37367904, 2023). "Epidemiological evidence for the association of insulin and insulin-related traits with incident colorectal cancer has been inconclusive, particularly among Asians8–11." (PMID 37120602, 2023). "One of the pathways in which the polymorphism of the involved genes is related to colorectal cancer is the insulin-signaling pathway." (PMID 37845622, 2023). "Two studies have reported that the higher insulinemic potential of diet or lifestyle is related to increment risk of various insulin-related malignancies, such as multiple myeloma, colorectal cancer, and digestive system cancer." (PMID 35578225, 2022). "High insulin levels have been linked to an increased risk of multiple cancers, including colorectal cancer." (PMID 35383926, 2022). "We quantified the mediating roles of C‐reactive protein (CRP), leptin, fasting insulin, and estradiol in the effect of adiposity on estrogen receptor (ER)‐positive breast, endometrial, and colorectal cancer risk in postmenopausal women." (PMID 35048536, 2022). "The meta-analysis showed a link between increased pre-diagnostic blood levels of insulin and glucose and the development of pancreatic and colorectal cancers." (PMID 34208601, 2021). "In this regard, a significant association has been observed between these indices and the risk of some insulin-related malignancies, including colorectal cancer, digestive system cancer, and multiple myeloma, previously." (PMID 33985566, 2021). "Possible mechanisms underlying the increased colorectal cancer risk include direct actions of IGF‐1 on cell growth or indirect effects via for example insulin resistance and elevated insulin levels." (PMID 32717139, 2020).
colorectal cancer (continued). "The expression of miR-103/107 has been shown to regulate systemic glucose metabolism and insulin sensitivity and has been associated with many types of cancers, including colorectal cancers." (PMID 32994328, 2020). "Post-diagnosis insulin index and insulin load have been linked to higher risk of dying from colorectal cancer." (PMID 32854644, 2020). "In previously published literature, insulin use has been associated with increased and metformin with decreased incidence of colorectal cancer." (PMID 33585194, 2020). "Higher dietary insulin load and insulin index after diagnosis of colorectal cancer were associated with increased risk of colorectal cancer-specific and overall mortality." (PMID 32854644, 2020). "Dietary fibre intake associates with overall metabolic health (through key pathways that include insulin sensitivity) and a variety of other pathologies that include cardiovascular disease, colonic health, gut motility and risk for colorectal carcinoma." (PMID 33096647, 2020). "Polymorphism of insulin gene and its association with colorectal cancer were demonstrated by some studies." (PMID 29793481, 2018). "Insulin levels are increased in diabetic patients treated with exogenous insulin and this has been showed to be associated with an increased risk of colorectal cancer in patients with T2DM." (PMID 30413050, 2018). "Knowing that circulating insulin level is associated with prognosis of colorectal cancer, exercise induced reduction in circulating insulin level is a beneficial change observed in colorectal cancer survivors." (PMID 29698416, 2018). "Although evidence is limited, insulin use has been associated with increased and metformin with decreased incidence of colorectal cancer." (PMID 28060743, 2017). "Physical activity is related to both inflammation and colorectal cancer risk, and frequent physical activity is associated with lower systemic inflammation and improved insulin sensitivity." (PMID 27483316, 2016). "Our results also support the notion that metabolically healthy/overweight individuals, with normal insulin levels, are at reduced risk of colorectal cancer compared to their hyperinsulinaemic counterparts." (PMID 27046222, 2016). "For instance, higher circulating insulin levels have been previously associated with greater colorectal cancer risk." (PMID 27046222, 2016). "In the present study, we found a twofold excess risk of colorectal cancer in diabetic patients using insulin as compared with users of oral antidiabetic medications, with a significant increased risk with increasing duration of exposure." (PMID 27766252, 2016). "In subgroup analysis, long-acting insulin treatment significantly decreased the risk of lung, liver, and colorectal cancer." (PMID 25978841, 2015). "In clinical studies, high circulating insulin levels are independently associated with increased colorectal cancer risk." (PMID 24885616, 2014). "A total of four studies with one case-controls study and three cohort studies comparing the insulin therapy and colorectal cancer susceptibility were identified." (PMID 24175949, 2013). "Recent studies showed that diabetic medications and use of insulin therapy are associated with the risk and outcome or colorectal cancer patients." (PMID 23405123, 2013). "In conclusion, our analysis suggests that insulin therapy will significantly increase the risk of colorectal cancer." (PMID 24175949, 2013). "With one exception, previous studies of the association of insulin and glucose with colorectal cancer risk have included only baseline measurements." (PMID 22127286, 2012). "Several previous studies have examined the association of circulating insulin and/or glucose levels with risk of colorectal cancer." (PMID 22127286, 2012). "Colorectal cancer (CRC) is associated with lifestyle factors that affect insulin/IGF signaling, of which the insulin receptor substrate 1 (IRS1) is a key transducer." (PMID 22558377, 2012).
colorectal cancer (continued). "Elevated fasting glucose, fasting insulin, 2 hour levels of glucose and insulin after an oral glucose challenge, and larger waist circumference were associated with a higher risk of colorectal cancer." (PMID 15496224, 2004). "Whole grains, vegetables, legumes, and fruit are rich in fiber, which colonic microbiota convert into short‐chain fatty acids that may lower colorectal cancer risk by reducing carcinogen exposure and improving insulin sensitivity." (PMID 41542809, 2026). "The extensive scope of radical resection and prolonged surgical stimulation in patients with colorectal cancer can lead to insulin insensitivity, stress hyperglycemia, increased risk of postoperative complications, hindered wound healing, and increased risk of wound infection." (PMID 40568192, 2025). "Similarly, the IGF-1-IGF1R binding activates pro-mitogenic signals overlapping those of insulin are correlated with a higher risk of developing tumors such as colorectal cancer." (PMID 41178954, 2025). "Insulin therapy is associated with a 69% greater risk for colorectal cancer, which may result from the mitogenic and pro-survival effects of insulin on colorectal cancer cells." (PMID 41178720, 2025). "Colorectal cancer patients are predominantly middle-aged and elderly individuals (61.22 ± 11.10 vs. 57.64 ± 12 years old), with reduced metabolic function making them more susceptible to insulin resistance and impaired insulin secretion." (PMID 40568192, 2025). "Indeed, recent large-scale MR studies supported a significant association between fasting insulin and colorectal cancer risk." (PMID 37120602, 2023). "The weak association between MDIH and colorectal cancer risk may be surprising, given previous support for the insulin–colorectal-cancer hypothesis, especially in men." (PMID 37367904, 2023). "Other factors may include the diverse genetic instruments for insulin secretion, which might be associated with different colorectal cancer pathways." (PMID 37120602, 2023). "Higher fasting insulin is positively correlated with the risk of colorectal cancer." (PMID 38179409, 2023). "Similarly, a case–control study from Korea with 3,606 cases and 6,019 controls indicated that increased serum insulin levels and insulin insistence were significantly associated with the presence of colorectal cancer." (PMID 35530326, 2022). "In addition, epidemiological studies have determined a positive association between insulin and C peptide with an increased risk of colorectal cancer." (PMID 33672318, 2021). "Similarly, in a WHI case‐cohort study, a positive association between serum leptin concentration and colorectal cancer risk was found, even after adjustment for insulin concentrations." (PMID 33038280, 2021). "It has been reported that insulin has some associations with colorectal cancers pathogenicity." (PMID 30774812, 2018). "Diabetes medications have also been associated with colorectal cancer risk in some studies which suggested that insulin use may increase the risk, while metformin and thiazolidinedione use may reduce it." (PMID 27766252, 2016). "Insulin use is more strongly associated with increased risk of overall, pancreatic, and colorectal cancer, while metformin and thiazolidinediones areassociated with a lower risk of overall, liver, and colorectal cancer." (PMID 24830459, 2014). "Our findings provides the evidence that insulin therapy may contribute to the risk of colorectal cancer." (PMID 24175949, 2013). "It is unclear whether circulating insulin or glucose levels are associated with increased risk of colorectal cancer." (PMID 22127286, 2012). "We conducted a prospective study of colorectal cancer risk using the subsample of women in the Women's Health Initiative study whose fasting blood samples, collected at baseline and during follow-up, were analysed for insulin and glucose." (PMID 22127286, 2012).
colorectal cancer (continued). "Multiple lines of evidence suggest a role of hyperinsulinemia and insulin resistance in colorectal cancer, implicating that factors such as magnesium that influence insulin levels might affect colorectal cancer risk." (PMID 22415230, 2012). "Further, high glucose levels may increase colorectal cancer risk independently of insulin either by favouring the selection of malignant clones or by acting as a direct source of energy for neoplastic cells." (PMID 22127286, 2012). "High levels of insulin (or C-peptide, a marker for insulin production) may also increase risk of colorectal cancer." (PMID 22216097, 2011). "If high IGF-1 and high insulin underlie in part the high risk of colorectal cancer in Western countries, our findings suggest that vitamin D status may be one particularly important factor in such populations." (PMID 22216097, 2011). "In this study, we have used a candidate gene approach to examine the associations between colorectal cancer risk and 52 allelic variants distributed in 35 genes drawn from pathways of inflammation, metabolism of xenobiotics detoxification, one-carbon, insulin signaling, and DNA repair." (PMID 18992148, 2008). "Recently, magnesium intake was found to be associated with increased levels of adiponectin, which may improve insulin sensitivity; adiponectin was inversely associated with colorectal cancer risk among men." (PMID 17285123, 2007). "As overweight is related to decreased insulin sensitivity, this may suggest that magnesium is inversely associated with colorectal cancer risk through improved insulin sensitivity." (PMID 17285123, 2007). "Moreover, sleep deprivation may indirectly, via insulin metabolism, affect circulating levels of insulin‐like growth factor‐1, which were positively associated with colorectal cancer in a previous MR study." (PMID 32895918, 2021). "Thus, it is possible that PPARG rs1801282 C>G polymorphism may be a protective factor for colorectal cancer through insulin-related mechanisms." (PMID 29246001, 2017). "Furthermore, the protective effect of metformin may be overestimated due to the association between insulin using and higher risk of colorectal cancer." (PMID 27926481, 2017). "Therefore, we conducted a longitudinal study of colorectal cancer risk in which fasting serum insulin and glucose levels were measured at baseline and during follow-up in a subsample of participants in the Women's Health Initiative (WHI) clinical trials (CTs) and observational study (OS)." (PMID 22127286, 2012). "However, we note that to date the epidemiologic evidence for a positive association of both fasting insulin and glucose with colorectal cancer risk in menopausal women is weak, but that for glucose may be somewhat stronger." (PMID 22127286, 2012). "However there is some evidence that positive associations between higher C-peptide/insulin levels and colorectal cancers may be more pronounced in men than in women." (PMID 22216097, 2011). "Serum C-peptide, a bio-marker of insulin secretion, is positively associated with colorectal cancer risk in humans and is regulated by dietary factors; however, relevance of insulin to suppressive effects of fruit consumption on colorectal cancer development is unclear." (PMID 19758446, 2009). "Meanwhile, RPTOR, a crucial component of the mTOR pathway, regulates cell growth in response to nutrient and insulin levels and has been reported as a key driver gene in the brain metastasis of lung and colorectal cancer progression." (PMID 41226303, 2025). "In colorectal cancer survivors, aerobic programs of ~150 min/week have been shown to reduce fasting insulin." (PMID 41178954, 2025). "According to relevant studies, UC (20 μM) affects insulin secretion in vitro in pancreatic cells and UC (20, 50 μM) has anticancer properties in colorectal cancer cells." (PMID 38849679, 2024).